IL13 (interleukin 13)
Diseases named in the same sentence as IL13 in open-access papers (continued):
Sharing a sentence is not in itself a finding about the gene and the disease.
asthma (continued). "Children with asthma had higher levels of IL-2 (p = 0.005), IL-5 (p < 0.001), IL-13 (p = 0.021), IL-17A (p < 0.001), IL-22 (p < 0.001), IL-33 (p < 0.001), TNF-α (p < 0.001), and lower levels of IL-10 (p = 0.046) and leptin (p < 0.001) compared to those without asthma." (PMID 39902293, 2024). "Rheological studies characterizing the biophysical properties of mucus plugs in patients with asthma show abnormally high elastic behavior, and characterization of inflammation in patients with asthma with mucus plugs shows upregulation of IL-13 in the airways." (PMID 38889046, 2024). "Both TGF-β and IL-13 contribute to airway remodeling in asthma." (PMID 38997751, 2024). "IL-13 is a plausible mediator of mucus plug formation in asthma because transgenic mice overexpressing IL-13 in their airways show mucus plugging, and IL-13–activated human airway epithelial cells (HAECs) form pathologic mucus gels with markedly reduced mucociliary movement." (PMID 38889046, 2024). "Inflamed airways show high levels of IL-13 (asthma), IL-8 or IL-6 (COVID-19; cytokine storm,)." (PMID 37979051, 2024). "As a crucial cytokine in asthma, IL-13 participates in the Th2 inflammatory response." (PMID 38335422, 2024). "In experimental models of asthma, female mice, after allergen challenge, have increased airway hyperresponsiveness, eosinophil influx, and more cytokine type 2 production (IL-4, IL-5, and IL-13) compared to males." (PMID 39840271, 2024). "Some pro-inflammatory cytokines relevant to asthma are interleukin (IL)-4, IL-13, IL-17, and IFNγ." (PMID 39197446, 2024). "The degree of the disease’s severity is associated with the abundance of type 2 innate lymphoid cells (ILC2s); patients with severe asthma exhibit higher counts of IL-5 and IL-13 secreting ILC2s in their sputum compared to those with milder forms of the condition." (PMID 38680486, 2024). "Also, at high dosages, tiotropium decreased the total number of inflammatory cells, including macrophages and eosinophils, and the levels of transforming growth factor-β1, IL-4, IL-5, and IL-13 in bronchoalveolar lavage fluid in a mouse model of asthma." (PMID 38419021, 2024). "Notably, IL-13 can induce B cell class switching and the production of immunoglobulin E (IgE), collectively exacerbating the progression of asthma." (PMID 39346946, 2024). "Dupilumab is a humanized monoclonal antibody targeting interleukin-4 and interleukin-13 cytokines currently indicated for moderate-to-severe atopic dermatitis, severe asthma, chronic rhinosinusitis with nasal polyposis, and moderate-to-severe prurigo nodularis." (PMID 39185064, 2024). "Additionally, a study conducted with asthma patients also demonstrated decreased IL-5 and IL-13 levels with omalizumab treatment, further supporting this theory." (PMID 38795119, 2024). "Additionally, the metabolomic remodeling was successfully monitored in connection with the histamine and corticosteroid treatment of the IL-13-induced asthma model." (PMID 38732251, 2024). "In asthma-susceptible neonatal BALB/c mice, RvE2 reduced eosinophil counts and IL-4, IL-5 and IL-13 levels, suggesting that RvE2 may prevent asthma risk." (PMID 39720728, 2024). "T2 inflammation-associated genes analysis revealed the association between eosinophils and IL-13, suggesting that these pathways may contribute to airway remodeling and mucus production in COPD, similar to mechanisms seen in asthma." (PMID 39766355, 2024). "Other studies on human airway cells aimed to explain two key aspects of asthmatic pathology: (i) the reprogramming of epithelial cells, leading to increased MUC5AC expression and mucus secretion, and (ii) the effects of IL-13 on epithelial cells, which are related to IL-13-induced asthma." (PMID 39684345, 2024). "IL-13 is increased in patients with airway disease, including asthma and COPD." (PMID 39255033, 2024).
asthma (continued). "Interestingly, the degree of IL-13 expression in ILC2 was greatest in patients with uncontrolled asthma compared to subjects with partly or well-controlled asthma and healthy controls." (PMID 38540714, 2024). "Compared with OVA sensitization or hyperoxia exposure alone, the mice in the model group (O2+OVA) showed asthma-like symptoms and increased airway hyperreactivity,The levels of IL-5,IL-13 IL-17A were increased in BLAF,and total leukocyte and eosinophil counts were also significant increasesed." (PMID 38148813, 2024). "Notably, IL-4, IL-13, and eotaxin play a significant role in the eosinophilia characteristic of asthma." (PMID 38668459, 2024). "Overexpression of IL-13 in the lungs elevates the production of mucus, goblet cell hyperplasia, eosinophilic tissue inflammation, fibrosis in the airway, crystal deposition, eotaxin production, atopic diseases, and asthma." (PMID 39239465, 2024). "There is a possibility that IL-4R or TSLPR is induced or increased in eosinophils from patients with severe asthma or atopic dermatitis, and these eosinophils may respond to IL-4, IL-13, or TSLP at concentrations up to 10 nM." (PMID 39624446, 2024). "Cytokines like IL-4, IL-5, and IL-13 often propel this immune reaction in asthma." (PMID 39407835, 2024). "In addition, biologics targeting IL-4/1L-13 (dupilumab) and IL-13 (i.e., lebrikizumab) have been shown to suppress serum periostin levels in asthma patients." (PMID 37108417, 2023). "Moreover, by secreting IL-13, iNKT cells promote the contraction of airway smooth muscle, which is a cardinal feature of asthma." (PMID 37917548, 2023). "miR-155 also plays a role in IL-13 that is related to inducing mucus production in asthma." (PMID 37374157, 2023). "Specifically, chitinases actively participate in IL-13-driven development of the Type 2 immune response in asthma or TGF-β-driven tissue repair in pulmonary fibrosis in animal models induced by non-chitin-containing insults, namely ovalbumin and bleomycin, respectively." (PMID 36902148, 2023). "Hunninghake G.M., Soto-Quirós M.E., Avila L., Su J., Murphy A.,Demeo D.L., Ly N.P., Liang C., Sylvia J.S., Klanderman B.J.,Lange C., Raby B.A., Silverman E.K., Celedón J.C. Polymorphismsin IL13, total IgE, eosinophilia, and asthma exacerbations in childhood.J." (PMID 37465198, 2023). "In addition, reduced Aqp5 mRNA and AQP5 protein levels were detected in lungs from an interleukin-13-induced mouse model of asthma." (PMID 36768212, 2023). "Notably, IL-13 and IL-6 have been widely recognized for their significant involvement in asthma pathogenesis." (PMID 38078005, 2023). "Furthermore, we were able to investigate relationships between sputum periostin and type 2 cytokines (IL-4 and IL-13) in a smaller, unrelated subset of 30 patients with asthma." (PMID 36763690, 2023). "Pharmacologically active IL-13 inhibitors, such as pitrakinra (an IL-4 mutant), tralokinumab, or the soluble IL-13Rα2, have already been clinically tested for the treatment of other diseases, such as asthma or in tumor therapy." (PMID 37629063, 2023). "In summary, many factors are involved in the variable response of asthma patients to SARS-CoV-2 infection, including the asthma phenotype, the corticosteroid treatment regimen and the role of cytokines such as IL-33 and IL-13 in potentiating the T2-high response." (PMID 37679779, 2023). "IL-13 is suspected of being the main mediator for triggering asthma attacks." (PMID 37629063, 2023). "Several anti-IL-13 drugs for the cure of asthma and atopic dermatitis are in clinical trials." (PMID 37041520, 2023). "Though airway epithelial knock-down of PIAS1 is sufficient to attenuate IL-13-induced airway goblet cell metaplasia, its potential role in allergen-induced mouse model of asthma remains unknown." (PMID 37393345, 2023).
asthma (continued). "T2 airway inflammation in patients with asthma, although occurring along a continuum, is characterized by a specific set of cytokines, including IL-4, IL-5, IL-13, and the so-called alarmins, IL-25 and IL-33, and thymic stromal lymphopoietin (TSLP), secreted by activated epithelial cells." (PMID 37947596, 2023). "RV infection of humans or mice upregulates Th2 inflammatory markers, including interleukin-13 (IL-13), interleukin-25 (IL-25), and interleukin-33 (IL-33), which may induce RV-driven exacerbation of asthma symptoms and drive remodeling." (PMID 37773065, 2023). "Here, we hypothesized that SFA such as PA is increased in asthma patients with obesity, which exacerbates type 2 airway inflammation in part by modulating IL-13-mediated release of soluble dipeptidyl peptidase 4 (DPP4)." (PMID 37287831, 2023). "Female-biased expression of IL-13 in asthma patients may interrupt tight junction proteins, contributing to worse asthma symptoms in females." (PMID 36882807, 2023). "Very briefly, the role of periostin, a matricellular protein, in asthma is believed to involve elevated production by structural cells in response to IL-13 secreted by activated T-helper 2 cells or type 2 innate lymphoid cells, which in turn can lead to increased airway fibrosis." (PMID 36763690, 2023). "The T2 high-associated increase in FeNO levels could be decreased by combined inhibition of IL-4 and IL-13 signalling in 104 patients with persistent, moderate-to-severe asthma." (PMID 40980110, 2023). "Moreover, the Th2-secreted cytokines IL-4 and IL-13 induce fibrosis by promoting fibroblast invasion in lungs of asthma patients." (PMID 37655660, 2023). "As a result of increased expression of DPP-4, which is induced by the type 2 cytokines interleukin (IL)-4 and IL-13, in diseases of asthma and type 2 inflammation, such as atopic dermatitis and chronic rhinitis, DPP-4i may help with the management of asthma." (PMID 37025413, 2023). "Decreasing the Th2-associated cytokines IL-4, IL-5, and IL-13, and increasing the Th1 cytokine IFN-γ may help to alleviate the inflammatory response in asthma." (PMID 36846048, 2023). "Preclinical studies in mouse models defined a role for IL-13 in many of the pathophysiologic features of asthma, including eosinophil recruitment, AHR, and tissue remodeling, as described by mucus hypersecretion, matrix dysregulation, and smooth muscle hyperplasia." (PMID 37163370, 2023). "Currently, several inhaled antibody fragments targeting, e.g., thymic stromal lymphopoietin (TSLP), tumor necrosis factor receptor 1 (TNFR-1), and interleukin-13 (IL-13), are under clinical investigation for the treatment of pulmonary diseases, particularly asthma." (PMID 37514028, 2023). "This study showed that transcriptomic analysis of BECs identified a downregulation of inflammation with the modulation of asthma-related relevant canonical pathways such as IL-13 and S100A alarmins downstream of IL-17 signaling as potential gene family regulated by BT treatment." (PMID 37996952, 2023). "Because IL-13 is a pivotal cytokine in T2-type asthma, this study opens up new ways to study the potential regulatory function of hY3 over IL-13 production and its implications for asthma development." (PMID 36089628, 2023). "In asthmatic bronchial fibroblasts, the effect of IL-13 has recently been linked to the pathologic involvement of the histone demethylase JMJD2B/KDM4B, which is a major contributor in the development of steroid-resistant asthma." (PMID 37655660, 2023). "In asthma, IL-4 plays a main role in regulating type 2 cell expansion and type 2-related cytokine production, as well as, IgE synthesis, while IL-13 has a major role in inducing the clinical features of the disease such as mucus production and airway hyperresponsiveness." (PMID 37753208, 2023).
asthma (continued). "Neonatal hyperoxia exposure promotes the development of asthma-like features including large infiltration of inflammatory cells around the bronchi, increased airway eosinophilia, and upregulated expression of the type 2 cytokines IL-5 and IL-13." (PMID 37485534, 2023). "While IL-13 is a key mediator in the onset of asthma, by playing an active role in IgE production, mucus hypersecretion, airway fibrosis and hyperreactivity to inhaled spasmogens, it also is the dominant cytokine in the induction of tissue fibrosis associated with chronic inflammation." (PMID 37483614, 2023). "Furthermore, an increased proportion of IL‐5+ILC2s and IL‐13+ILC2s was observed in PBMCs of patients with asthma, particularly in the EA group." (PMID 37357549, 2023). "Dupilumab could also improve antiviral immune response in patients with severe T2 asthma on account of IL-4 and IL-13 by damaging the production of viral-induced IFN that expresses TLR3." (PMID 37685567, 2023). "IL-13 is a key inducer of mucus production and the increased abundance of goblet cells in asthma." (PMID 37445635, 2023). "Furthermore, IL-4 and IL-13 activate the M2 macrophage subtype in patients with either asthma and/or CRSwNP." (PMID 37240477, 2023). "Additionally, GGsTop was also successful in attenuating IL-13-induced airway hyperreactivity and mucous production, suggesting that there is therapeutic potential for this compound in the treatment of asthma." (PMID 37377967, 2023). "A potentially protective effect of pre-existing atopic conditions such as asthma and allergies in COVID-19 patients has been observed in other studies, and eosinophilia and IL-13 activation have been hypothesized as possible mechanisms behind this effect." (PMID 37243062, 2023). "Interestingly, in severe asthma patients treated with anti-IL13 drugs, elevated FeNO levels appeared to be related to a better clinical control." (PMID 36829959, 2023). "Earlier findings have also shown that cigarette smoke could exacerbate ovalbumin‐induced asthma and markedly enhance the expression of IL‐4 and IL‐13 genes." (PMID 36789047, 2023). "In this sense, it has been confirmed that G-1 possesses encouraging therapeutic potential for asthma treatment, since it diminished airway hyperresponsiveness and inflammation (decrease in IL-5 and IL-13 levels in bronchoalveolar lavage fluid) in asthma models." (PMID 37895016, 2023). "Thus, type 2 cytokines, such as IL-4, IL-5, and IL-13, are promising therapeutical targets for AR and also other allergic diseases, such as asthma and atopic dermatitis." (PMID 37109185, 2023). "Interestingly, we observed elevated frequencies of IFNγ+IL-5+, IFNγ+IL-9+, and IFNγ+IL-13+ double-producing Tc cells, supporting type-2 skewing of IFNγ+ Tc1 cells in asthma." (PMID 37612281, 2023). "Furthermore, expression of genes whose expression correlates with asthma, including Il9, Il4, Il13, Ccl11, Ccl24, and Muc5ac, was much lower in recipients of Id1 cKO Th9 cells." (PMID 37867222, 2023). "Type 2 inflammation occurs in approximately 70% of severe asthma patients and is promoted by a broad network of hyper-expressed cytokines, namely IL-4, IL-5, IL-13, and several immune cells, including mastocytes, type-2 helper lymphocytes, type-2 innate lymphoid cells, basophils, and eosinophils." (PMID 37298514, 2023). "However, the results from clinical trials in asthma patients treated with mAbs specific for IL-13 have thus far been disappointing." (PMID 37163370, 2023). "Biologic drugs, such as anti-IgE and anti-IL-5, anti-IL-4/IL-13 monoclonal antibodies, are currently being used with clinical success in patients with type-2 diseases, such as asthma and CRSwNP, and only recently some authors suggested their efficacy also in the treatment of comorbid EOM." (PMID 35207196, 2022). "Dupilumab might also improve antiviral immune responses in patients with T2-high asthma because IL-4 and IL-13 impaired viral-induced IFN production and TLR3 expression." (PMID 36077310, 2022).
asthma (continued). "Moreover, we found a significant decrease in the level of IL-13 in both asthma and COPD patients, which was measured as a biomarker of obstructive airway diseases in our study." (PMID 35677382, 2022). "Furthermore, the NLRP1 deficient mice showed increased IL13 levels in BAL, suggesting a protective effect for NLRP1 in the context of asthma." (PMID 36189256, 2022). "They explained these results by stating that polymorphic variants of the IL-13 gene are not the only direct cause of diseases such as asthma." (PMID 35629280, 2022). "Additionally, IL-33 promoted the ILC production of IL-13 in asthma patients, whereas it promoted the natural killer cell production of IFN-γ in control subjects." (PMID 36077310, 2022). "In T2 asthma, the Th2 cytokines IL-4, IL-5, IL-9, IL-13, and IL-25, and the acute proinflammatory cytokines TNF-α, IL-1β, IL-6, and IL-8, subsequently lead to bronchial hyperresponsiveness (BHR), and plasma cells and antibody-producing cells secrete antibodies." (PMID 36430662, 2022). "This study aimed to investigate the role of CLCA1 and IL-13 in pediatric asthma." (PMID 36313877, 2022). "A mouse asthma model was given oral/pulmonary administration of AG nanoformulation, and the bioavailability of the drug was greatly enhanced, as was the release of inflammatory factors (such as IL-4, IL-5 and IL-13), which were also significantly reduced." (PMID 35455087, 2022). "Although studies revealed that SMD can attenuate asthma by regulating the expression of inflammatory mediators such as of INF-γ, IL-4, IL-10, IL-13, and TNF-α, the exact mechanism underlying its protective effect remains unclear." (PMID 36578267, 2022). "In addition, sputum IL-13 levels in patients with poorly controlled asthma are higher than those in patients with well-controlled asthma." (PMID 36560620, 2022). "In this study, IL-13 inhibition through SAC administration could ameliorate asthma-related inflammatory events by downregulating Th2 cytokines." (PMID 36555240, 2022). "As a cytokine of Th2 cells, IL-13 is the central mediator of asthma." (PMID 36699060, 2022). "Given the finding that phosphorylated STAT6 is the primary target for degradation upon PARP-1 inhibition, this represents a unique opportunity to target the transcription factor for degradation during asthma where the IL-4/IL-13/STAT6 pathway is upregulated especially in uncontrolled/severe disease." (PMID 36348405, 2022). "IL-4 and IL-13 play separate pathophysiologic functions in asthma." (PMID 36483465, 2022). "One such example is Tralokinumab, a human anti-IL-13 monoclonal antibody for uncontrolled asthma." (PMID 35327141, 2022). "Consequently, blocking of IL-13 signaling was successful in preventing asthma symptoms in animal models." (PMID 35997279, 2022). "Moreover, several let-7 family miRNAs namely, miR-1, mir-19, miR-126, miR-155, and miR-221, that regulate Th2 inflammatory responses by downregulating IL-13 and VEGF, are known for their association with asthma pathogenesis." (PMID 36264868, 2022). "Our results revealed that the expression of the autophagy-marked protein (LC-3) was enhanced in lung tissues of asthma mice and bronchial epithelial cells stimulated with IL-13, and the expression of autophagy related proteins (NCOA4, TFR1, and DMT-1) in these cells and tissues were also promoted." (PMID 35154576, 2022). "We also found the potential effects of herbal medicines in relieving overall respiratory symptoms in asthma and improving the symptoms of dyspnoea and quality of life in COPD patients, as well as inhibiting IL-13 levels in both asthma and COPD patients, with a high level of patient satisfaction." (PMID 35677382, 2022). "Furthermore, in a mouse model of HDM-induced asthma, gonadectomy in female mice significantly reduced the proportion of IL-13+ and IL-17A+ T cells; in contrast, gonadectomy in male mice significantly increased the proportion of IL-13+ and IL-17A+ T cells." (PMID 35625578, 2022).